SOX1 (SRY-box transcription factor 1)
Diseases named in the same sentence as SOX1 in open-access papers (continued):
Sharing a sentence is not in itself a finding about the gene and the disease.
cancer (continued). "In the second diagnostic evaluation 229 scrapings were analyzed for SLC6A5, SOX1, SOX14 and TBX20 hypermethylation using the QMSP threshold values that were set in the normal and cancer samples." (PMID 27738327, 2016). "Except for TBX5, all 5 genes (GFRA1, SLC6A5, SOX1, SOX14 and TBX20) were significantly differentially methylated between normal and cancer tissues with a high methylation frequency in both ADC and SCC." (PMID 27738327, 2016). "The methylation levels of PAX1, SOX1, and ZNF582 showed significant elevation in cancer patients." (PMID 40256126, 2025). "No malignancies were detected following comprehensive cancer surveillance in the single patient in our series with NP-LEMS who was seropositive for SOX1 up to 11 years from the diagnosis of LEMS." (PMID 39734633, 2024). "In the stage of reactivation, some QCCs may decrease SOX1 and re-express MYC protein, resulting in increased abundance of proliferative cancer cells." (PMID 37369660, 2023). "Overexpression of SOX1 in H1299 and CL1-0 cells significantly decreased cancer cell growth." (PMID 37190139, 2023). "Unlike cancer stem cells with self-renewal ability to maintain their proportion in tumors, the SOX1-induced QCCs did not exhibit similar characteristics." (PMID 37369660, 2023). "The three best-performing genes exhibited individual frequencies of 53.0–71.0% in serum CFDNA, and the multiplex assay for these genes were identified to discriminate serum from cancer patients and healthy individuals (area under the curve: HOXA9+HIC1 = 0.95, HIC1+SOX1 = 0.93 and HOXA9+SOX1 = 0.85)." (PMID 34778370, 2021). "Methylated HOXA9, SOX1, and HIC1 exhibited the highest sensitivity, specificity, AUC, and accuracy for cancer detection in both singleplex and multiplex MethyLight assay, thereby asserting that their promoter hypermethylation was highly cancer-specific." (PMID 34778370, 2021). "There is currently no information with regards to PTMs affecting SOX1 protein function in either neural stem cells or cancer." (PMID 33202879, 2020). "These suggest that hypermethylation of SOX1 and PAX1 might play an important role in the diagnosis and cancer progression of CAC." (PMID 33376722, 2020). "The presence of a few SOX1-positive cancer cells within tumor lesions might indicate that traditional chemotherapy fails to eliminate all cancer cells, even if the patient has achieved a complete response." (PMID 37369660, 2023). "Furthermore, 66.7% of patients with positive anti-SOX1 abs do not have malignant tumors; therefore, anti-SOX1 abs can only be used as a reference index rather than a diagnostic standard." (PMID 37083806, 2023). "The function of SOX1 and POU4F3 in cancer biology remain largely unknown." (PMID 26057869, 2015).
tumor (47 papers, 2009 to 2025). "Since increased cell motility and invasion are key drivers of metastasis, the methylation-induced silencing of SOX1 likely facilitates tumor dissemination, and is thus associated with poorer clinical outcomes in NSCLC patients." (PMID 40699796, 2025). "Since rapid growth of tumor is the main cause of poor prognosis, we investigated the impact of SOX1 on the growth of CCA." (PMID 34876142, 2021). "Possibly, the increased resistance to cisplatin treatment is due to the increased expression of these CSC-associated proteins (Nanog and Sox1) observed in the tumor spheroids." (PMID 30651721, 2019). "Through explore the clinicopathologic characteristics of patient, we found that low level of SOX1 was associated with large tumor size (P < 0.05), which indicate that SOX1 may associated with proliferation of tumor." (PMID 34876142, 2021). "Moreover, <5% of tumor samples in the TCGA cohorts had mutations in the SOX1 gene, indicating that SOX1 might exert its function through alteration of its own RNA/protein levels." (PMID 37369660, 2023). "The percentage of SOX1+ cells increased in advanced-stage hSCLC tumours, whereas that of MCT4+ cells remained unchanged." (PMID 39939778, 2025). "SOX1 has been shown to act as a tumor suppressor by antagonizing the Wnt/β-catenin signaling pathway." (PMID 40699796, 2025). "This cluster was enriched in genes involved in differentiation and developmental processes (for example, SOX1 and SOX9, HOXD3 and HOXD8, and TBX4) and genes implicated as tumor suppressors (for example, SOX1 and SOX17, TSHZ3, WT1-AS, and FGF14)." (PMID 40931149, 2025). "SOX21 plays a tumor suppressor role in central nervous system tumors as a complexing SOX1–3 inhibitor." (PMID 40141294, 2025). "Specifically, SOX1 can interact with β-catenin and prevent its transcriptional activity, thereby inhibiting Wnt target gene expression and limiting tumor progression." (PMID 40699796, 2025). "The mean tumor weight was significantly lower in the SOX1-transfected NOD/SCID mice than in the vector control mice (p < 0.001)." (PMID 37190139, 2023). "Taken together, these data demonstrated that SOX1 acts as a tumor suppressor by directly inhibiting HES1 during the development of NSCLC." (PMID 37190139, 2023). "Our study presents an evolutionary trade-off between tumor growth and chemoresistance orchestrated by SOX1-MYC in NPC." (PMID 37369660, 2023). "To evaluate the influence of SOX1 expression on tumor growth, we subcutaneously injected tumor cells expressing SOX1 into NOD/SCID mice." (PMID 37190139, 2023). "To further confirm the tumor suppressor function of SOX1, we applied a Tet-on inducible system to manipulate SOX1 expression." (PMID 37190139, 2023). "This further supports the finding that tumor cells with high expression of SOX1 lack growth advantage in a stress-free environment." (PMID 37369660, 2023). "Our data further verified that the restoration of SOX1 expression represses tumor growth and metastasis in xenograft models." (PMID 37190139, 2023). "Using a model that mimics therapeutic resistance and tumor recurrence, a subpopulation of SOX1-induced NPC cells is refractory to paclitaxel, a cell cycle-specific chemotherapy drug." (PMID 37369660, 2023). "Overexpression of HES1-FLAG in SOX1-expressing H1299 cells partly reversed the tumor-suppressive effect of SOX1 expression compared with the control." (PMID 37190139, 2023). "Accumulating evidence has demonstrated the close relation of SOX1 with tumorigenesis and tumor progression." (PMID 34876142, 2021). "Overexpression of SOX1 significantly inhibited cell proliferation in vitro and suppressed tumor growth in vivo." (PMID 34876142, 2021). "In tumor sections, expression of Sox1, Sox9, and Map2 was obvious in undifferentiated cells and differentiated neural tissue." (PMID 33468253, 2021).
tumor (continued). "Site S93 was the only experimentally verified phosphorylation site reported for the human SOX1 protein, found phosphorylated in tumour tissue affected by ischemia." (PMID 33202879, 2020). "SOX1 inhibits cell proliferation, reduces migration and invasion ability, and induces differentiation of tumor cells." (PMID 32382038, 2020). "The expression of SOX1 in the tumor biopsies varied between 0.12 and 133 fold change when compared to normal brain tissue, with 18 of 26 tumors showing greater than 1.5 fold change in SOX1 levels." (PMID 28425506, 2017). "When compared with the control group, the mean tumor volume and tumor weight were significantly lower in mice inoculated with SOX1-overexpressing CNE2 cells." (PMID 25427424, 2014). "Consistently, SOX1 is a tumor suppressor that is suppressed by hypermethylation of its promoter region in cervical and ovarian cancers." (PMID 25427424, 2014). "CNE2 cells stably transfected with either empty vector or SOX1 were delivered subcutaneously into nude mice and tumor growth was monitored." (PMID 25427424, 2014). "SOX1 mRNA expression was significantly down-regulated in primary NPC tissues when compared with the adjacent non-tumor tissues." (PMID 25427424, 2014). "To further demonstrate the anti-tumor function of SOX1, we knocked down SOX1 with transient siRNA transfection in CNE2 and HONE1 cells stably overexpressing SOX1." (PMID 25427424, 2014). "We selected 5 CpG loci with significant methylation differences by tumor histology (q-value < 2.2E-16 and fold-change > 2.50) for validation by Pyrosequencing (HOXA9_E252_R, SOX1_P294_F, WT1_E32_F, WNT2_P217_F, MDR1_seq_42_S300_R)." (PMID 23806198, 2013). "Interesting findings include that SOX2 regulates the expression of SOX family proteins SOX1 and SOX18, and that SOX2 down regulates BEX1 (brain expressed X-linked 1) and BEX2 (brain expressed X-linked 2), two genes with tumor suppressor activity in GBM." (PMID 21211035, 2011). "Furthermore, we performed phenotypic rescue experiments to prove that overexpression of HES1-FLAG in SOX1-expressing H1299 cells partly reversed the tumor-suppressive effect." (PMID 37190139, 2023). "Our findings raised the intriguing question why a tumor suppressor like SOX1 could have a negative regulation on the prognosis of late-stage HNSC patients." (PMID 37369660, 2023). "We also detected five mutations (ALOX2B, JAK1, PGR, RUNX1, SOX1) in the HGSOC41.1 tumor sample but not in the corresponding PDO." (PMID 37202753, 2023). "Our results provide a proof of concept and suggest that SOX1 might perform its tumor-suppressive function by inhibiting the expression of HES1." (PMID 37190139, 2023). "However, in the “SOX1-High” group, the QCCs were able to undergo stress and reactivate, mimicking tumor recurrence." (PMID 37369660, 2023). "However, low frequency of genetic alterations is observed in SOX1, suggesting that this tumor suppressor has a secondary mechanism for unfavorable prognosis." (PMID 37369660, 2023). "Our results suggest that SOX1 might perform its tumor-suppressive function by inhibiting the expression of HES1." (PMID 37190139, 2023). "We found a statistically significant association between LMX1A methylation and tumor size (p = 0.0048) but did not observe significant associations between SOX1 or ZNF177 methylation and any of the clinicopathological parameters." (PMID 31547144, 2019). "In order to determine whether the mechanism by which SOX1 regulates proliferation and tumor growth is specific to GSCs or it is broader, we knocked-down SOX1 expression in the U251 cell line." (PMID 28425506, 2017). "Indeed, SOX1 knockdown significantly impaired self-renewal and proliferative capability in vitro and tumor initiation and tumor progression in vivo." (PMID 28425506, 2017). "Moreover, genetic inhibition of SOX1 in patient-derived GSCs and conventional cell lines decreases self-renewal and proliferative capacity in vitro and tumor initiation and growth in vivo." (PMID 28425506, 2017).
tumor (continued). "Next, we examined the influence of SOX1 on NPC cells tumor formation in vivo." (PMID 25427424, 2014). "In hypermetylated genes, SOX1 expression decreased in tumor tissues significantly (p = 0.0107)." (PMID 23735005, 2013). "One possible explanation for the differential expression of Sox1, Oct4 and Klf4 in low and high grade tumors, is that these tumor types may constitute distinct disease entities." (PMID 21483788, 2011). "In summary, our work has identified that SOX1 expression is highly enriched in the pool of GSCs and its inactivation significantly impairs their malignant properties including proliferation, ability of self-renewal, differentiation capacity as well as tumor initiation and progression." (PMID 28425506, 2017). "Interestingly, SOX1 silencing significantly delayed tumor-forming capacity of GNS166 cells." (PMID 28425506, 2017). "The elevated methylation levels of SOX1 and HOXA9 in tumor samples compared to normal lung tissue and blood samples indicate that these epigenetic alterations are specific to NSCLC." (PMID 40699796, 2025). "This study analyzed the methylation status of SOX1 and HOXA9 in 63 primary NSCLC tumor samples, corresponding normal lung tissues, and circulating blood, using bisulfite pyrosequencing." (PMID 40699796, 2025). "SOX1 and HOXA9 promoter methylation levels were significantly higher in tumor tissues compared to normal lung tissues and blood samples." (PMID 40699796, 2025). "Serological testing revealed a marked elevation of tumor markers, along with the presence of anti-CV2/CRMP5, anti-Hu, and anti-SOX1 antibodies." (PMID 41542009, 2025). "Our study elucidated the function of the transcription factor SOX1 in the regulation of colony formation and invasion in NSCLC cells, implying its function as a tumor suppressor (TSG)." (PMID 37190139, 2023). "We used lentiviruses to alter the expression of SOX1 in CCA cells, and assessed the effects using CCK-8 assay, plate clone assay, flow cytometry and in subcutaneous tumor-bearing mice." (PMID 34876142, 2021). "The promoter methylation levels of selected candidate genes (RASSF1A, DAPK1, SOX1, HOXA9, HIC1, SPARC, and SFRP1) were quantitatively evaluated by MethyLight in tumor DNA samples of patients with EOC." (PMID 34778370, 2021). "These oncogenes, such as GDNF, STAT3, and SOX1, induce CAF activation and promote the overexpression of growth factors such as CXCL12 and Wnt/Notch for differentiating epithelial cells into tumor-initiating stem cells." (PMID 34513834, 2021). "The methylation level in the methylated EOC tumor samples ranged from 4 to 97% for HOXA9; 7–89% for HIC1; 4–97% for SOX1; 4–95% for DAPK1; 5–97% for SFRP1; 6–99% for SPARC and 4–98% for RASSF1A gene, respectively." (PMID 34778370, 2021). "Overall, these results suggested that SOX1 inhibited the proliferation of CCA cells in vitro and tumor growth in vivo." (PMID 34876142, 2021). "miR-155 inhibits SOX1 expression through combining with the 3’UTR of SOX1, promoting migration of tumor cells." (PMID 35155211, 2021). "Large areas of intense staining of SOX1, SOX9 and MAP2 suggested that cells with neural stemness and neuronal features were among the major cell types in tumor." (PMID 33468253, 2021). "Autoantibodies to SOX1 are common in small-cell lung carcinoma (SCLC) and serve as a serological tumour marker for SCLC, while the role of a SOX1-related autoimmune response in SCLC is still elusive." (PMID 33202879, 2020). "SOX antibodies have become useful markers of SCLC in these PNDs, most notably in LEMS, where SOX1 and SOX2 antibodies have been found in 64–78% of patients with SCLC and LEMS compared with only 0–5% in non-tumour LEMS patients." (PMID 30445363, 2019). "Several recent studies have shown that STAT3 transcriptionally regulates key tumor-driving genes that are essential for tumor pathogenesis, such as TNFRSF1A, MCY and SOX1." (PMID 31747963, 2019).
tumor (continued). "Therefore, we tested whether SOX1 silencing could regulate tumor initiation performing subcutaneous inoculation of serial diluted U251 cells transduced with empty vector or both shSOX1 constructs (sh1 and sh5) in immunodeficient mice and by performing oncosphere formation assays." (PMID 28425506, 2017). "Ectopic expression of SOX1 in NPC cells suppressed colony formation, proliferation and migration in vitro and impaired tumor growth in nude mice." (PMID 25427424, 2014). "We focused in those genes that were significantly differently methylated in the basal-like tumor subtype (HOXA9, SOX1, VAMP8, and TNFRS10D) and those that were significantly hypermethylated in the luminal B tumors (NPY, RASSF1, HS3ST2, DBC1, FGF2, CD40." (PMID 20920229, 2010). "We suggest to re-classify the intrinsic transcriptional factor SOX1 as a “tumor hypnotist” rather than a “tumor suppressor”, based on its dynamic roles in tumor development." (PMID 37369660, 2023). "In the “SOX1-Low” group, proliferative cells underwent cell-cycle phase under paclitaxel treatment and lived no longer than 7 days, mimicking tumor regression." (PMID 37369660, 2023). "In addition, we noted that in tumor samples the expression level of MEG3, TIMP, DAPK1 and SOX1 was lower, while the expression of MLH1 and MALAT1 was higher in comparison to the normal samples." (PMID 35682732, 2022). "Furthermore, the quantitative evaluation of gene promoter methylation through MethyLight assay was confirmed and validated by clonal bisulfite sequencing of selected tumor tissue and normal DNA samples for HOXA9, HIC1, and SOX1 gene." (PMID 34778370, 2021). "IHC revealed expression of Sox1, Sox9, Map2, Acta2, Bglap and Afp in sections, indicating the presence various types of neural and non-neural tissues or cells in tumor." (PMID 33468253, 2021). "In summary, we found that SOX1 is downregulated expression in CCA patients, it suppressed the RAF/MEK/ERK pathway by decreasing the phosphorylation of RAF, MEK, and ERK, and inhibited the proliferation of CCA cells in vitro and suppressed tumor growth in vivo." (PMID 34876142, 2021). "SOX1 and SOX2 ELISA results were markedly concordant (>98%): one LEMS-SCLC patient and one non-tumour LEMS patient had positive SOX2 antibodies but negative SOX1 antibodies." (PMID 30445363, 2019). "These cells expressed high levels of PAX6 but had only low-level expression of SOX1, whereas the neural precursor stage, which did not result in any tumor formation, expressed high levels of both markers." (PMID 23928330, 2013). "In our results, a hypermethylated gene, SOX1 expression reduced in tumor tissue, whereas TJP2 expression did not reduce." (PMID 23735005, 2013). "We found that low level of SOX1 was associated with tumor size (P < 0.05), but not with age, gender, lymph node metastasis and TNM stage, which indicate that SOX1 may associated with proliferation of tumor." (PMID 34876142, 2021). "To determine whether SOX1 exerts a tumor-suppressive function, we investigated the growth-suppressive effect of SOX1 by restoring SOX1 expression in H1299, H23, and CL1-0 cells, which display no detectable SOX1 expression." (PMID 37190139, 2023). "Indeed, in the PRP130 GEMM, we also found that both SOX1 (marking NE cells) and MCT4 (marking non-NE cells) were completely absent in PNEC and NEB (PNEC/NEB) but appeared in mSCLC tumours, and they were expressed by completely distinct subpopulations in both mSCLC and hSCLC tumours." (PMID 39939778, 2025).
infection (4 papers, 2013 to 2025). The state of being infected such as from the introduction of a foreign agent such as serum, vaccine, antigenic substance or organism. "To gain insight into the potential mechanisms underlying the phenotypic changes, we carried out RNA-seq analysis in Sox1/3Δ/Δ and Sox2F/F or Sox1/3Δ/Δ; Sox2F/F before and after Cre infection." (PMID 40216251, 2025). "Interestingly, Sox1, a marker specific to the neuroectodermal lineages, was markedly upregulated following infection with HCMV." (PMID 24144363, 2013). "In support of this idea, RNA-Seq and RT-qPCR analysis revealed that the expression of Sox3,but not Sox1, increased immediately after lenti-Cre infection of Sox2F/F ESCs and reached a peak around day 9 and then remained at that level thereafter." (PMID 40216251, 2025).
peripheral neuropathy (3 papers, 2021 to 2023). A disorder affecting the peripheral nervous system. "Only a small number of patients without PNS are positive for anti-SOX1 abs or have PNS with unknown etiology, which mainly manifests as peripheral neuropathy, indicating that anti-SOX1 abs may mediate peripheral nerve-related immune responses." (PMID 37083806, 2023).
neurological disorders (2 papers, 2019). "Anti-SOX1 antibodies' positive paraneoplastic neurological disorders are rare and are usually associated with small cell lung cancer (SCLC)." (PMID 31880403, 2019).
adenocarcinoma (1 paper, 2013). A common cancer characterized by the presence of malignant glandular cells. "The co-methylation of SIX6 and SOX1 was negatively associated with adenocarcinoma (ADC) with an odds ratio (OR) of 0.24 (95% CI, 0.06–0.90)." (PMID 23599765, 2013).